AQP1 (aquaporin 1 (Colton blood group))
Diseases named in the same sentence as AQP1 in open-access papers (continued):
Sharing a sentence is not in itself a finding about the gene and the disease.
cyst (12 papers, 2010 to 2026). A sac-like closed membranous structure that may be empty or contain fluid or amorphous material. "al. described how the overexpression of AQP1 inhibited cyst growth in a MDCK cyst model, while the deletion of AQP1 promoted cyst development in an embryonic kidney and a PKD mouse model." (PMID 40428321, 2025). "A MDCK cyst model also demonstrated that the overexpression of AQP1 inhibited cystogenesis and increased MDCK cell branching." (PMID 32365994, 2020). "Neuropathological examination demonstrated marked ChP epithelial disorganization, reduced aquaporin-1 (AQP1) expression, cyst formation, and focal calcifications, which may be associated with disturbances in cerebrospinal fluid (CSF) dynamics." (PMID 42051775, 2026). "The data presented that overexpressing AQP1 inhibited cyst growth in MDCK cyst model." (PMID 30654539, 2019). "Contrarily, deletion of AQP1 promoted cyst development in embryonic kidney and PKD mice." (PMID 30654539, 2019). "The cyst location was determined by IHC staining for AQP1 and AQP2." (PMID 30235266, 2018). "Thus, this cyst type may precede the formation of AQP1- or AQP2-positive cysts and may represent the earliest manifestation of the disease, although long-term monitoring is required for definite proof." (PMID 31822676, 2019). "The possible roles of increased expression of AQP-1 in the etiology of different neuropathological conditions are still unknown, but it is likely that AQP-1 up-regulation may contribute to edema and cyst formation-typical outcomes in most of these pathological conditions." (PMID 20969805, 2010). "Our results correspond with formerly published observations regarding AQP1 and AQP2 and their role in cyst formation and development." (PMID 40428321, 2025). "In ADPKD, altered localization or reduced expression of AQP1 and AQP2 disrupts standard water transport mechanisms, contributing to cyst formation and progression." (PMID 40428321, 2025). "AQP1 expression was seen in within cysts and AQP1 expression decreased as ADPKD progressed and cyst size increased." (PMID 34843700, 2022). "Upon KO of AQP1 in a PKD mouse model, investigators observed an increase in kidney size and cyst formation, together with increased Wnt signalling activity in the kidney." (PMID 32365994, 2020). "To identify the tubular segment involved in cyst formation, we stained for different tubular segment markers, i.e., aquaporin 2 (AQP2) for collecting ducts, CD13 and aquaporin 1 (AQP1) for proximal tubules and Tamm–Horsfall protein (THP) for the thick ascending limb (TAL)." (PMID 35055068, 2022).
diabetes (12 papers, 2010 to 2024). "We show here that concentrations of glucose attainable in diabetes induce COX-2 in human endothelial cells through an AQP1-dependent hyperosmolar mechanism and, through this mechanism, promote angiogenesis." (PMID 26822858, 2016). "In contrast, modulation of retinal AQP1 and AQP4 expressions was observed during experimental diabetes; AQP1 expression was induced on glial cells and in the innermost retinal layers." (PMID 20383338, 2010). "Although AQP1 was mainly expressed in the outer retina, it can also be observed in the innermost retinal layers following experimental damage-inducing neural retina edema, and altered glial cell-mediated water transport, diabetes, and ischemia." (PMID 37958666, 2023). "The association of AQP1 and NFAT5 co‐expression with aortic stiffness in diabetes and hypercholesterolaemia may represent a novel molecular pathway or therapeutic target." (PMID 31970899, 2020). "Moreover, urine DNMTs/AQP1 expression was significantly correlated with the annual eGFR decline rate after adjustment for age, baseline eGFR, the presence of diabetes and the amount of albuminuria, suggesting a possible role as a renal prognosis predictor." (PMID 32099032, 2020). "Finally, urine DNMTs/AQP1 expression was significantly correlated with the annual eGFR decline rate after adjustment for age, baseline eGFR, the presence of diabetes and the amount of albuminuria." (PMID 32099032, 2020). "Future in vivo investigations using AQP1 overexpression or knockdown mice may be useful to determine the therapeutic utility of AQP1 in diabetes." (PMID 27383386, 2016). "Moreover, Aqp1 was claimed to be directly involved in aortic stiffening in diabetes." (PMID 38965173, 2024). "As with AQP1, the results for AQP2 expression in animals with induced (by STZ) diabetes are contradictory." (PMID 38791455, 2024). "Aqp1 plays a key role in the maintenance of amniotic fluid homeostasis, and its expression level can be decreased with the deepening of insulin resistance during pregnancy, which may explain the frequent abnormal amniotic fluid homeostasis in pregnant women with diabetes." (PMID 36107823, 2022). "We did not observe significant differences in the expression of AQP1 between the diabetic control group and the non-diabetic control group, perhaps because the period after the induction of diabetes was too short." (PMID 38791455, 2024). "The absence of AQP1 and NFAT1 knockout mice having the comorbidities of diabetes and hypercholesterolaemia complicates the performance of this type of experiments." (PMID 31970899, 2020).
lung adenocarcinoma (12 papers, 2014 to 2025). A carcinoma that arises from the lung and is characterized by the presence of malignant glandular epithelial cells. "Increased AQP-1 expression has been associated with angiogenesis and lung adenocarcinoma." (PMID 38334585, 2024). "In lung adenocarcinoma cells, AQP1 overexpression correlated with the downregulation of E-cadherin and the upregulation of vimentin." (PMID 35847914, 2022). "AQP1 was mainly up-expressed in lung adenocarcinoma (ADC) and bronchoalveolar carcinoma (BAC) instead of lung squamous cell carcinoma and normal lung tissue." (PMID 25886458, 2015). "AQP1 overexpression in lung adenocarcinoma was associated with EMT markers: loss of E-cadherin (epithelial marker) and increased expression of vimentin (mesenchymal marker), indicating the involvement of AQP1 in EMT and consequent invasive potential." (PMID 39941100, 2025). "Moreover, in lung adenocarcinoma cells, AQP1 overexpression showed certain cellular characteristics of EMT, including decreased expression of E-cadherin and increased expression of known EMT regulated proteins, such as vimentin and N-cadherin." (PMID 35847914, 2022). "Previous reports showed that the expression of AQP1 was overexpressed in lung adenocarcinoma." (PMID 30042826, 2018). "AQP1 is upregulated in lung adenocarcinoma, and, inhibition of AQP1 inhibits tumor cell invasion." (PMID 30555637, 2018). "Notably, we previously found AQP1 to be differentially expressed between lung adenocarcinomas and squamous cell carcinomas." (PMID 24917931, 2014).
ovarian carcinoma (12 papers, 2015 to 2023). A malignant neoplasm originating from the surface ovarian epithelium. "AQP1 upregulation at transcript and protein levels in ovarian cancer cells was associated with increased cancer growth, while deletion of AQP1 reduced growth, migration, and invasion." (PMID 33499000, 2021). "In our current study, we discovered overexpression of AQP1 mRNA was associated with poor OS for all ovarian cancer patients, especially for serous ovarian cancer, with well and moderate differentiation (pathological grades I and II) as well as in all clinical stages (I–IV)." (PMID 29472315, 2018). "In detail, when ovarian carcinomas were divided by histological types, low AQP1 expression correlated with poorer prognosis in clear cell variant, while high AQP1 content has been related to poorer prognosis in mucinous and endometrioid carcinomas." (PMID 33807998, 2021). "Only few studies have investigated the pathogenetic and prognostic role of β-catenin and AQP1 in ovarian carcinoma." (PMID 33807998, 2021). "In malignant forms of ovarian cancer, a much higher expression of AQP1, AQP5, AQP9 was observed compared to benign forms of ovarian cancer or normal ovaries." (PMID 33271827, 2020). "AQP1 mRNA expression level revealed a remarkable correlation with worse OS amongst all the ovarian cancer patients, HR = 1.21 (1.06–1.38), P=0.0036." (PMID 29472315, 2018). "Based on previous evidences as well as our results, we can acknowledge that AQP0, AQP1, and AQP4 high mRNA expression were significantly associated with poor prognosis in ovarian cancer patients." (PMID 29472315, 2018). "In detail, authors demonstrated a statistically significant association between AQP1 expression and poor chemotherapy omental response (CRS1-2), suggesting that AQP1 could represent a predictive biomarker of platinum resistance in ovarian cancer." (PMID 35328186, 2022). "Recently, in a gynaecological context, some Authors have immunohistochemically evaluated the expression of AQP1, 3, 5, and 9 in a total of 300 ovarian carcinomas using tissue microarrays, by demonstrating that AQPs can be considered useful prognostic markers in ovarian carcinoma." (PMID 33807998, 2021). "Malignant ascites, the most common complication of ovarian cancer, could involve AQP1 in the pathological accumulation of fluids out of blood vessels into the peritoneal cavity, secondary to increased permeability of capillaries and upregulation of VEGF." (PMID 33499000, 2021). "Research indicates that AQP1, 3, 5, and 9 expression may become useful biological markers in ovarian cancer prognosis, but their correlation with a prognosis depends on the type of cancer present." (PMID 33271827, 2020). "Additionally, AQP3, AQP6, and AQP11 mRNA expression were correlated with better OS, whereas AQP0 and AQP1 showed poor OS in all ovarian cancer patients treated with Platin, Taxol, and Taxol + Platin chemotherapy." (PMID 29472315, 2018). "Our data may stimulate future research in expanding the comprehension of platinum-resistance mechanisms in ovarian cancer, since we retain the water permeability regulation of AQP1 may play an important role in drug metabolism and drugs chemo-sensitivity as elsewhere previously reported." (PMID 33807998, 2021). "Aquaporin 1 (AQP1), as component of transmembrane-water-channel family proteins, has been documented in different human tumors and, recently, also in ovarian carcinoma." (PMID 33807998, 2021).
ovarian carcinoma (continued). "Ginsenoside was found to inhibit migration of prostate cancer cells in vitro by inhibiting AQP1-dependent pathways, while curcumin was found to inhibit AQP3-mediated cancer cell migration in human ovarian cancer cells." (PMID 33499000, 2021). "On the other hand, mRNA expression of AQP1 (grades I and II), AQP4 (grades I, II, and III), AQP6/2L (grade I), AQP10 (grade II) showed a worse OS in ovarian cancer patients." (PMID 29472315, 2018). "Our results revealed that higher AQP0, AQP1, and AQP4 mRNA expression were correlated with poor OS, whereas higher AQP3, AQP5, AQP6, AQP8, AQP10, and AQP11 showed better OS in ovarian cancer patients." (PMID 29472315, 2018). "Whereas AQP1 (stages I + II and III + IV), AQP4 (stages I + II and III + IV), and AQP5 (stage I + II) expressions revealed remarkably unfavorable OS in all ovarian cancer patients." (PMID 29472315, 2018). "Intriguingly, when concurrent (Platin + Taxol) treatment and prognostic significance were analyzed, the data showed that high expression of AQP0 and AQP1 mRNA were correlated to decrease survival rate and high expression of AQP3, AQP6, and AQP11 were correlated to good OS in ovarian cancer patients." (PMID 29472315, 2018). "CURC treatment was also found to downregulate AQP1 in rat choroid plexus cells, useful to reduce cerebrospinal fluid production in some pathophysiological conditions, and AQP3 expression in human ovarian cancer cells." (PMID 29292793, 2017). "However, the correlation with prognosis depends on the histological type of ovarian carcinoma; specifically, high AQP5 expression is related to poorer prognosis in serous carcinoma, while low AQP1 expression was evident in clear cell carcinomas with poorer prognosis." (PMID 33807998, 2021). "However, the prognostic value of AQP1 in ovarian cancer has not yet been studied." (PMID 29472315, 2018).
cerebral edema (11 papers, 2018 to 2025). "Nonetheless, this is the first study to demonstrate the role of inhaled Au-NPs in causing brain edema in vivo, involving Au-NP-mediated AQP1 induction in the endothelial cells of brain tissues." (PMID 31619255, 2019). "In the central nervous system, two major aquaporins (AQPs), AQP1 and AQP4, and their potential involvements have been long implicated in the pathophysiology of many brain disorders such as brain edema and Neuromyelitis optica." (PMID 37047501, 2023). "Aquaporin-1(AQP1) is also involved in the formation of cerebral edema, while AQP1 inhibitors, such as fullerenols, can reduce cerebral edema." (PMID 33613264, 2020). "This hints at the nose-to-brain delivery of nanoparticles, which can be correlated with Au-NP-mediated AQP1 expression and cerebral edema." (PMID 31619255, 2019). "For example, downregulation of AQP1 inhibits tumour blood vessel proliferation and tumour metastasis and reduces cerebral oedema." (PMID 29554889, 2018). "Consequently, inhibiting the synthesis of TTF-1 increased the survival rate of animals with acute water intoxication-induced brain edema by suppressing AQP1 expression." (PMID 39944892, 2025). "Additionally, AQP1 and AQP4 can help predict post-burn or post-traumatic cerebral edema, and genetic mutations in AQP1 and AQP9 can indicate the risk of SIDS." (PMID 38473914, 2024). "On the contrary, the occurrence of cerebral oedema from a damaged BBB may be compensated by a reduction in AQP-1." (PMID 35151337, 2022). "Whether cerebral oedema in CM is prevented by a decline in AQP-1 needs further investigation." (PMID 35151337, 2022). "Furthermore, AQP1 might be a good indicator of brain edema severity and manipulation of AQP1 could be of benefit to the treatment of distinct brain edema subtypes." (PMID 36010640, 2022). "There is an urgent need to develop specific AQP inhibitors and activators to explore the potential benefits of modulating the functions of AQP1 and AQP4 in the context of brain edema." (PMID 39944892, 2025). "Moreover, given the important role of AQP1 in CSF production, AQP1 was proposed to participate in hydrocephalic brain edema resulting from the increase in CSF pressure and BBB disruption, and its threefold increase in expression levels in hydrocephalic brain edema supported this hypothesis." (PMID 36010640, 2022).
hepatocellular carcinoma (11 papers, 2016 to 2025). A malignant tumor that arises from hepatocytes. "It is important to note that, in some cases, such as hepatocellular carcinoma, increased expression of AQP1 is associated with the vasculature, and rarely the cancer cells themselves." (PMID 32679804, 2020). "Our previous study shows that AQP1 has different roles in human cancers, including chronic myeloid leukemia (CML), hepatocellular carcinoma, and cervical cancer." (PMID 32903818, 2020).
lung injury (11 papers, 2014 to 2023). "W. Liang and colleagues have shown that AQP1 expression is down-regulated in lung tissue during CLP-induced acute lung injury in rats." (PMID 37490500, 2023). "Earlier research has established that AQP1, AQP4, AQP2 and AQP9 are associated with spinal cord injury- or nerve injury-induced nerve pain in rats." (PMID 35324416, 2022). "Previous studies have showed that AQP1 protein expression decreases significantly in LPS-induced acute lung injury." (PMID 32566670, 2020). "Also, noncoding RNAs interacting with AQP1, were involved in the development of acute lung injury." (PMID 34814929, 2021). "Lipopolysaccharide-induced acute lung injury significantly impaired alveolar fluid clearance; however, following administration of dopamine, this symptom was relieved (via upregulation of AQP1 and AQP5 expression), which may have further promoted the reabsorption of alveolar fluids." (PMID 25009607, 2014). "AQP5, but not AQP1, showed suppressed expression in smothering compared with expression in strangulation and sudden cardiac death and death from acute brain injury." (PMID 34977094, 2021).
lymph node metastasis (11 papers, 2014 to 2025). "AQP1 has traditionally been recognized as a water channel protein, and many studies have shown its association with carcinogenesis, metastasis, poor prognosis, lymph node metastasis, and cellular migration 61-63." (PMID 40386053, 2025). "We performed immunohistochemistry analysis in 194 cases of invasive ductal carcinoma (IDC), and found that high cytoplasmic expression of AQP1 was positively associated with metastasis or recurrence (P = 0.009), lymph node metastasis (P = 0.038), tumor size (P = 0.003), and pTNM stage (P = 0.003)." (PMID 36803413, 2023). "Additionally, a significant association was identified between decreased AQP1 expression and the presence of lymph node metastasis." (PMID 37904849, 2023). "For example, we found that AQP1 was upregulated in tumors from patients with LNM, and the upregulation of AQP proteins has been reported to associate with lymph node metastasis, recurrence, and low overall survival rate in multiple cancers." (PMID 36520032, 2023). "In the analysis of their clinicopathological features, AQP1 expression of cytoplasm dominance groups correlated with pathological lymph node metastasis stage (p=0.028)." (PMID 30042826, 2018). "Our results showed that AQP1 expression of cytoplasm dominance groups correlated with pathological lymph node metastasis stage (p=0.028)." (PMID 30042826, 2018). "Expression of AQP1 was positively correlated with histological grade, tumor size, pTNM stage, lymph node metastasis and recurrence or distant metastasis." (PMID 26812884, 2016). "Clinical stage, tumor diameter, lymph node metastasis, tumor infiltration depth, serum SCC-Ag level, HPV infection status, treatment protocol, and expression of AQP1 and AQP3 were associated with cumulate survival rate in cervical cancer." (PMID 24918928, 2014). "Patients with more advanced TNM stage, infiltration depth, and lymph node metastasis had increased serum COX-2, AQP1, and G-17 levels and decreased PG-I levels (P<0.05)." (PMID 39634909, 2024). "Spearman correlation analysis showed that serum levels of COX-2, AQP1, and G17 were significantly positively correlated with TNM staging, infiltration depth, and lymph node metastasis (P<0.05), and significantly negatively correlated with the degree of differentiation (P<0.05)." (PMID 39634909, 2024). "Cytoplasmic expression of AQP1 was higher in patients with lymph node metastasis than that in patients without lymph node metastasis." (PMID 26812884, 2016). "AQP1 expression in patients with lymph node metastasis was higher than that in patients without metastasis." (PMID 26812884, 2016).